HIF1A (hypoxia inducible factor 1 subunit alpha)
Diseases named in the same sentence as HIF1A in open-access papers (continued):
Sharing a sentence is not in itself a finding about the gene and the disease.
sarcoidosis (8 papers, 2012 to 2023). Sarcoidosis is a multisystemic disorder of unknown cause characterized by the formation of immune granulomas in involved organs. "HIF1α is known as a central gate keeper in Mɸ metabolism and is predominantly expressed in pulmonary granulomas in sarcoidosis, where HIF1α increases Glut1 expression and levels of IL-1β in alveolar Mɸ and monocytes." (PMID 36902053, 2023). "The regulatory effect of HIF-1α on IL-1β expression has been studied in the context of sarcoidosis, infections, and cancer." (PMID 34497517, 2021). "The transcription factor HIF-1α was immunodetected in MD-macrophages both in normoxic and hypoxic conditions, similarly between sarcoidosis and control groups HIF-1α was immunolocalized in the cytoplasm and nucleus of MD-macrophages." (PMID 34456926, 2021). "HIF-1α expression has recently been found to be upregulated in sarcoidosis CD14 monocytes and associated with regulation of IL-1β and IL-17 production; here, we confirmed upregulation of HIF1A in these cells." (PMID 33363531, 2020). "Under normoxic conditions we found enhanced expression and activity of HIF-1α in sarcoidosis AMs and monocytes." (PMID 30946009, 2019). "In the current study, we applied a combination of transcriptional and functional approaches to investigate the role of HIF-1α in mediating the inflammatory immune response in AMs, monocytes, and PBMCs of sarcoidosis patients as compared to healthy controls." (PMID 30946009, 2019). "In contrast to our study one prior study reported decreased HIF-1α mRNA and protein expression in sarcoidosis tissue biopsies, although the same study reported increased expression of VEGF, which is directly regulated by HIF." (PMID 30946009, 2019). "HIF-1α protein expression was further confirmed in granulomatous lung tissue from sarcoidosis patients, and was found to be localized to alveolar macrophages and multinucleated giant cells." (PMID 31681260, 2019). "Down regulation of HIF-1α expression via short interfering RNA (siRNA) decreased IL-1β in sarcoidosis AMs, while decreased HIF-1α expression in PBMCs decreased IL-1β and IL-17 in response to anti-CD3 challenge." (PMID 30946009, 2019). "Abundance of HIF-1α in sarcoidosis also implies aberrant degradation by proteasomal or/and lysosomal pathways." (PMID 30946009, 2019). "Downregulation of HIF-1α via siRNA or chemical inhibitors in sarcoidosis PBMCs leads to a decrease in IL-6 and IL-17 production at baseline and in response to anti-CD3 stimulation." (PMID 30946009, 2019). "Immunofluorescence staining of sarcoidosis AMs showing presence of HIF-1α in the cytoplasm and nuclei." (PMID 30946009, 2019). "To further explore the expression seen in sarcoidosis AMs, we assessed the presence of HIF-1α in lung biopsies of patients with sarcoidosis." (PMID 30946009, 2019). "Targeted downregulation of HIF-1α via siRNA of sarcoidosis AMs led to a significant reduction (about 50%) in HIF-1α and pro-IL-1β protein expression." (PMID 30946009, 2019). "Western analysis of cell lysates probed with antibody against HIF-1α showed increased HIF-1α protein expression in sarcoidosis AMs and monocytes." (PMID 30946009, 2019). "We therefore utilized high-throughput microarray technology and computerized image analysis seeking to determine the expression of HIF-1a-VEGF-ING4 axis in lung biopsy samples from patients with sarcoidosis of stages II-III." (PMID 23181555, 2012). "Notably, we too discerned the activation of HIF1A in our TREM2_2 macrophages, indicating a shared transcriptional response of macrophages in sarcoidosis patients." (PMID 38038136, 2023). "In normoxia, HIF-1α was similarly activated at a very low level in controls and sarcoidosis groups." (PMID 34456926, 2021). "Furthermore, in situ HIF-1α immune staining of sarcoidosis lung biopsies demonstrated HIF-1α abundance in the center of granulomatous tissue and in multinucleated giant cells." (PMID 30946009, 2019).
sarcoidosis (continued). "Similarly, we observed increased HIF-1α immunostaining signal in sarcoidosis liver and skin tissue samples." (PMID 30946009, 2019). "We quantitated the percentage of cells showing HIF-1α expression in sarcoidosis." (PMID 30946009, 2019). "Environmental factors, altered metabolism, and inflammation can be linked to epigenetic changes such as methylation and acetylation that may contribute to HIF-1α expression and stability in sarcoidosis." (PMID 30946009, 2019). "Increased HIF-1α expression in sarcoidosis AMs and granulomatous sarcoidosis lung tissue." (PMID 30946009, 2019). "In our current work, we found significantly higher HIF-1α expression in sarcoidosis AMs and PBMCs." (PMID 30946009, 2019). "Similarly, we evaluated the HIF-1α protein abundance in isolated monocytes from sarcoidosis subjects and healthy controls and found significantly higher HIF-1α expression." (PMID 30946009, 2019). "Furthermore, increased pro-IL-1β expression directly correlated with Glut1 and HIF-1α expression in sarcoidosis AMs." (PMID 30946009, 2019). "Furthermore to gain a holistic view regarding the hypoxia-angiogenesis axis within granulomatous lesions in sarcoidosis patients we investigated the expression of HIF-1a repressor gene, ING4." (PMID 23181555, 2012). "Our results represent the first attempt in the literature investigating the expression and immunolocalization of HIF-1a-VEGF-ING4 axis within sarcoid lesions shedding further light in the understanding of the pathogenesis of sarcoidosis, favoring the infectious etiology concept." (PMID 23181555, 2012). "It is therefore impossible to conclude a causal-effect relationship between decline of HIF-1a expression and upregulation of VEGF and ING4 since HIF-1a may have been simply consumed and exerted its functions by the time diagnosis of sarcoidosis was established based on tissue findings." (PMID 23181555, 2012). "Several studies in sarcoidosis reported the expression of HIF-target genes within lung and lymph node granulomas, while HIF-1α expression was inconsistently found." (PMID 34456926, 2021). "For example, here, among other genes, STAT1, IL10RA, and PTEN were underexpressed in sarcoidosis CD14 monocytes compared to controls while CXCR4, ATG12, HIF1A, CCR1, and IER3 were overexpressed, consistent with the effects of TGFB1 signaling." (PMID 33363531, 2020). "In accordance with this, a recent study demonstrated elevated protein levels of HIF-1α, as well as HIF-1α signaling pathway components such as HIF-1β, HIF-2α, and p300, in alveolar macrophages from sarcoidosis patients cultured under normoxic conditions." (PMID 31681260, 2019). "We found that a higher percentage of CD14+ monocytes express HIF-1α and HIF-2α in sarcoidosis subjects as compared to controls." (PMID 30946009, 2019). "HIF-1a and VEGF-ING4 expression, both in protein and mRNA level, was found to be downregulated and upregulated, respectively, in sarcoidosis samples compared to controls." (PMID 23181555, 2012). "qRT-PCR was used to assess HIF-1a and ING4 expression in 10 sarcoidosis mediastinal lymph node and 10 control lung samples." (PMID 23181555, 2012). "Here, we show that sarcoidosis AMs and monocytes in normoxic ex vivo culture conditions and without any stimulation exhibit constitutively active HIF-1α and HIF-1β (ARNT) along with its coactivator, p300." (PMID 30946009, 2019). "We observed that a p38 inhibitor (SB203580) partly decreased the expression of HIF-1α (data not shown) and cytokine levels in sarcoidosis." (PMID 30946009, 2019). "Interestingly, CHQ decreased LAMP2 levels and both HIF-1α (by approximately 50%) and HIF-2α protein expression (by approximately 65%) in sarcoidosis AMs after LPS stimulation." (PMID 30946009, 2019). "We hypothesized that CHQ modulates LAMP2, HIF-1α, and HIF-2α levels and cytokine production in sarcoidosis AMs and PBMCs." (PMID 30946009, 2019).
sarcoidosis (continued). "To determine the relative contribution of increased HIF-1α in IL-1β production in sarcoidosis AMs, we transiently transfected sarcoidosis AMs with either non-targeted siRNA or HIF-1α targeted siRNA." (PMID 30946009, 2019). "To further confirm increased expression of HIF-1α protein in sarcoidosis and to determine whether HIF-1α accumulates in the nucleus, we immunostained AMs using specific an antibody against HIF-1α." (PMID 30946009, 2019). "Since HIF-1α is known to be predominantly regulated through modification of its protein stability, we evaluated HIF-1α and HIF-2α protein abundance in AMs and monocytes of sarcoidosis patients, isolated as described in Materials and methods." (PMID 30946009, 2019). "The identification of the mechanisms underlying the aberrant regulation of HIF-1α and HIF-2α leading to persistent inflammation and Th1/Th17 pathology in sarcoidosis should open new avenues in rational drug discovery, not only for this disease but also for other inflammatory diseases." (PMID 30946009, 2019).
sarcopenia (8 papers, 2016 to 2026). Progressive decline in muscle mass due to aging which results in decreased functional capacity of muscles. "Given the significant role of myostatin in sarcopenia with ethanol, the mechanistic link between HIF1α and myostatin needs to be evaluated." (PMID 40308032, 2025). "In conclusion, in this work we found that HIF-1α plays a role in sarcopenia and is involved in satellite cell homeostasis." (PMID 35806119, 2022). "We found a decrease in the expression of HIF-1α and its target genes in sarcopenia, as well as of PAX7, the major stem cell marker of satellite cells, whereas the atrophy marker MURF1 was increased." (PMID 35806119, 2022). "To investigate the role of HIF-1α in sarcopenia, we first determined the atrophic phenotype of skeletal muscle biopsies from our sarcopenic patient cohort compared with biopsies from young individuals who served as controls." (PMID 35806119, 2022). "Mechanistically, HIF-1α contributes to sarcopenia through the glucagon-like peptide-1 (GLP-1) and nuclear factor kappa-B (NF-kB) catabolic pathway." (PMID 36364144, 2022). "Based on these findings, we envisioned the possibility of developing a novel pharmacological approach to sarcopenia that would counteract the decline of HIF-1α and its target genes." (PMID 35806119, 2022). "Based on these premises, in this work, we further investigated the role of HIF-1α in sarcopenia by studying human skeletal muscle biopsies from elderly patients affected by sarcopenia and comparing them with those from healthy individuals." (PMID 35806119, 2022). "As hypoxia has been proposed to be a potential contributing mechanism to sarcopenia, HIF-1α was quantified at the mRNA and protein levels." (PMID 26784225, 2016). "In this work, we investigated the role of the hypoxia inducible factor HIF-1α in sarcopenia." (PMID 35806119, 2022). "Thus, HIF-1α plays a role in sarcopenia and is involved in satellite cell homeostasis but need further research." (PMID 36364144, 2022). "Combined with results of previous studies, the findings presented here suggest that GPD1L could be a genetic biomarker for sarcopenia, based on both miR-210 and HIF-1α pathways." (PMID 35241739, 2022). "Although these results are still preliminary, they seem to support the notion that pharmacological activation of HIF-1α could counteract the development of sarcopenia by activating muscle regeneration." (PMID 35806119, 2022). "Mechanistically, HIF-1α deletion stimulates GLP-1 secretion in human adipocytes, which contributes to sarcopenia in hypoxia." (PMID 36364144, 2022). "An integrated multiomics approach, combined with experimental validation, identifies HIF1α stabilization and accelerated post‐mitotic senescence as novel mechanisms of sarcopenia in ALD." (PMID 40308032, 2025). "In renal diseases, the critical characteristic of HIF-1α is protective, but it also has a negative effect, such as in sarcopenia." (PMID 36364144, 2022). "In these models, the critical characteristic of HIF-1α is protective, but it also has a negative effect, such as in sarcopenia." (PMID 36364144, 2022).
ulcer (8 papers, 2012 to 2025). "In control patients, HIF-1α mRNA was slightly detected in specimens from the periphery of the ulcer; the values of HIF-1α increments were only 7% of the increments seen in biopsy of vildagliptin patients (P < 0.001)." (PMID 23197976, 2012). "Exogenous hADSCs promote ulcer repair and angiogenesis through HIF-1α." (PMID 32294623, 2020). "Notably, HIF-1α mRNA levels in specimens from the periphery of the ulcer were strongly dependent on proteasome activity, as also reflected by the statistically significant correlation between HIF-1α levels and proteasome 20S activity (R = 0.37, P < 0.01)." (PMID 23197976, 2012). "However, the significant correlation between proteasome activity and the reduction of HIF-1α levels in ulcer tissues suggests an involvement of the proteasome system in the impaired wound healing of diabetic lesion by decreasing angiogenesis process." (PMID 23197976, 2012). "However, in the normal wound healing process, HIF-1α expression can persist for approximately 7 days after injury, and the present findings may therefore reflect the sustained therapeutic effect on refractory ulcers." (PMID 41295064, 2025). "In control diabetic patients, the picture is quite different because both HIF-1α and VEGF levels were significantly lower than those in vildagliptin-treated ulcer specimens." (PMID 23197976, 2012). "In diabetic patients treated with vildagliptin, we detected increased steady-state levels of HIF-1α and VEGF in specimens from ulcers." (PMID 23197976, 2012). "Relative ulcer volume (RUV) was measured every month; biopsies were taken at baseline and months 1 and 2 for histopathology and gene expression analysis for COL-1α, COL-4, KGF, VEGF, ACTA2 (α-SMA), elastin, fibronectin, TGF-β1, TGF-β3, HIF-1α, and HIF-1β." (PMID 29675430, 2017). "Moreover, we have observed an increase of HIF-1α, VEGF, capillary density and a decrease of nitrotyrosine levels in the specimens obtained in ulcers of the vildagliptin group both compared to their baseline and control group." (PMID 23197976, 2012).
acute pancreatitis (7 papers, 2014 to 2025). An acute inflammatory process that leads to necrosis of the pancreatic parenchyma. "The aim of this study was to investigate the effects of hypoxia-inducible factor-1α (HIF-1α) and matrix metalloproteinase-9 (MMP-9) on alveolar-capillary barrier disruption and lung edema in rat models of severe acute pancreatitis-associated lung injury (PALI)." (PMID 25120621, 2014).
acute promyelocytic leukemia (7 papers, 2014 to 2025). An aggressive form of acute myeloid leukemia (AML), characterized by arrest of leukocyte differentiation at the promyelocyte stage, due to a specific chromosomal translocation t(15;17) in myeloid cells. "Lastly, recent data suggest that HIF-1α could be involved in promyelocytic leukemia/retinoic acid receptor-α (PML-RARα)-dependent resistance." (PMID 34202238, 2021). "Indeed, in vitro and in vivo studies performed in acute promyelocytic leukemia (APL) models demonstrated that HIF-1α levels increased upon the treatment with all-trans retinoic acid (ATRA)." (PMID 34202238, 2021). "After these first indications, we described a pro-leukemogenic function of HIF-1α in a specific sub-type of AML, that is acute promyelocytic leukemia or AML-M3, due to a specific functional cooperation of HIF-1α with the oncogenic fusion protein PML-RARα." (PMID 27447550, 2016). "Furthermore, Pin1 interacts with the CDK1/2 kinase and Cul3-KLHL20 Ub ligase to degrade promyelocytic leukemia (PML), which is a tumor suppressor that typically prevents HIF-1α translation by suppressing mTOR after HIF-1α activation." (PMID 38727267, 2024). "In patients with acute promyelocytic leukemia (APL), the combination of HIF-1α inhibitors with differentiation-inducing agents such as all-trans retinoic acid (ATRA) or arsenic trioxide (ATO) may have synergistic effects on promoting myeloid cell differentiation and improving treatment outcomes." (PMID 38351314, 2024). "In an acute promyelocytic leukemia (APL) model (PML/RARα), green tea treatment reduced blast percentages (CD34 and/or CD117) in the bone marrow and spleen possibly through the induction of apoptosis and reduction in the CXCR4/HIF-1α signaling pathway in response to a decrease in ROS levels." (PMID 37513933, 2023).